NLRC5 (NLR family CARD domain containing 5)
Description:
Probable regulator of the NF-kappa-B and type I interferon signaling pathways. May also regulate the type II interferon signaling pathway. Plays a role in homeostatic control of innate immunity and in antiviral defense mechanisms.
Synonyms: CLR16.1; NOD27; NOD4; FLJ21709
Tractability: PROTAC: ubiquitination databases record sites on it.
Gene: Protein-coding gene on chromosome 16 (56,989,485 to 57,084,238, forward strand). Ensembl gene ENSG00000140853.
Subcellular location: Cytoplasm
Subcellular location (Human Protein Atlas): Cytosol; Centrosome
Pathways (Reactome):
Immune System: DDX58/IFIH1-mediated induction of interferon-alpha/beta; Negative regulators of DDX58/IFIH1 signaling; Regulation of NF-kappa B signaling
Gene Ontology:
Molecular function: protein binding; RNA polymerase II cis-regulatory region sequence-specific DNA binding
Biological process: defense response to virus; innate immune response; negative regulation of canonical NF-kappaB signal transduction; negative regulation of type I interferon-mediated signaling pathway; positive regulation of MHC class I biosynthetic process; positive regulation of transcription by RNA polymerase II; positive regulation of type I interferon-mediated signaling pathway; positive regulation of type II interferon-mediated signaling pathway
Cellular component: cytoplasm; cytosol; nucleus
Genetic constraint (gnomAD): Loss-of-function variants: 112 observed, 201.29 expected, observed/expected ratio (o/e) 0.56, 90% interval 0.48 to 0.65. The upper end of that interval is the gene's LOEUF score, 0.65, which puts it in group 2 of 6, group 1 being the genes least tolerant of losing a copy. Missense variants: 1,998 observed, 2,341.2 expected, observed/expected ratio (o/e) 0.85, 90% interval 0.82 to 0.89. Synonymous variants: 948 observed, 977.83 expected, observed/expected ratio (o/e) 0.97, 90% interval 0.92 to 1.02.
Homologues: Orthologues: chimpanzee NLRC5 (99% identical), macaque NLRC5 (95% identical), dog NLRC5 (74% identical), pig NLRC5 (74% identical), guinea pig NLRC5 (70% identical), rabbit NLRC5 (66% identical), mouse Nlrc5 (64% identical), rat Nlrc5 (63% identical), tropical clawed frog nlrc5 (30% identical). Paralogues in human: NLRP12 (13% identical), NLRC3 (13% identical), NLRP3 (12% identical), NLRP4 (12% identical), NLRP9 (11% identical), NOD2 (11% identical), CIITA (11% identical), NLRP1 (11% identical), NLRP14 (11% identical), NLRP2 (10% identical), NLRP5 (10% identical), NLRP7 (10% identical), and 8 more.
Diseases named in the same sentence as NLRC5 in open-access papers:
NLRC5 is named in the same sentence as 138 diseases in open-access papers, as found by Europe PMC text mining. Sharing a sentence is not in itself a finding about the gene and the disease. The quoted sentences say what the papers report.
melanoma (31 papers, 2016 to 2025). A malignant, usually aggressive tumor composed of atypical, neoplastic melanocytes. "Methylation of NLRC5 in melanoma is associated with loss of MHC Class I genes HLA-A, HLA-C and B2M expression, which are linked to immunotherapy resistance and decreased survival." (PMID 40307913, 2025). "Recently, we (Rodriguez) provided the first evidence that enhanced NLRC5-driven MHC I expression increases the susceptibility of “hot” melanoma tumors to CD8+ T cell recognition." (PMID 38235131, 2023). "Increased expression of NLRC5 was associated with the slower growth of the tumor in a mouse melanoma model and prolonged survival time in patients with melanoma." (PMID 36268281, 2022). "Low expression of NLRC5 is associated with poor prognosis, low activity of immune-related signatures, low infiltrating level of immune cells, and low cytotoxic score in melanoma." (PMID 34307322, 2021). "Among 448 melanoma samples profiled for NLRC5 mutation, missense mutations were found in 32 samples (7.1%), truncating in 6 samples (1.3%), splice in 2 samples (0.4%), and multiple in 3 samples (0.7%)." (PMID 34307322, 2021). "NLRC5 expression is closely associated with Breslow thickness, Clark level, recurrence, pathologic T stage, and ulceration status in melanoma." (PMID 34307322, 2021). "Melanoma patients with both low NLRC5 expression and low mutation/neo-antigen load had the worst prognosis." (PMID 34307322, 2021). "This is consistent with the result that the low NLRC5 expression was associated with advanced T stage in melanoma." (PMID 34307322, 2021). "In this study, we have shown that low NLRC5 expression was associated with multiple worse clinical characteristics and prognosis in melanoma." (PMID 34307322, 2021). "We also used GSEA to explore signaling pathways associated with NLRC5 expression in melanoma by using Gene Ontology HALLMARK terms." (PMID 34307322, 2021). "In melanoma and bladder cancer, Low methylation of the NLRC5 promoter is associated with higher survival rate.Therefore, the NLRC5 methylation network plays a role in diseases and immunity, and its relationship with CNS diseases and specific disease mechanisms needs to be further elucidated." (PMID 34220868, 2021). "Taken together, these data indicate that multivariate analysis using NLRC5 expression/methylation status with mutation load is superior to single variable analysis and may be of value as a prognostic biomarkers in melanoma." (PMID 33547395, 2021). "Furthermore, mutation of NLRC5 was also observed in ∼10% of melanoma patients." (PMID 34307322, 2021). "Exemplary knockdown of NLRC5 and B2M by siRNA in three different melanoma cell lines confirmed that downregulation of the IFN-γ-induced STAT1 pathway indeed significantly impairs HLA-C expression and Vα3S1/Vβ13S1 TCR stimulation." (PMID 40243413, 2025). "Treatment of melanoma cells with hypomethylating agents can restore NLRC5, TAP1 and MHC Class I expression to promote immune recognition, and response to checkpoint blockade." (PMID 40307913, 2025). "According to previous literature reports, patients with high expression of NLRC5 have significantly longer survival periods compared to those with low expression in melanoma, rectal, bladder, uterine, cervical, and head/neck cancer." (PMID 39132868, 2024). "PRELPhigh melanoma cells express increased levels of NLRC5 as well as selected IFN-γ signal transduction molecules, e.g., IRF1, IRF5, STAT1 and STAT2." (PMID 37730606, 2023). "We show that expressing NLRC5-SA in B16 melanoma and EL4 lymphoma results in efficient tumor control in syngeneic mice." (PMID 37108368, 2023). "PRMT5 methylates IFI16/IFI204 and inhibits NLRC5 transcription, suppresses inflammation and antigen presentation, and promotes melanoma growth." (PMID 37163421, 2023). "We have shown that NLRC5-FL expression in B16 melanoma increases the expression of APM genes and the immunogenic potential of tumor cells." (PMID 37108368, 2023).
melanoma (continued). "We have previously shown that NLRC5-FL expression in B16.F10 melanoma cells reduces tumor growth by promoting CD8+ T cell activation and CTL-mediated tumor killing." (PMID 37108368, 2023). "In non-small-cell lung cancer, NLRC5 seems to be a negative indicator of prognosis, whereas in other types such as endometrial cancer and melanoma, NLRC5 downregulation has been correlated with poor prognosis." (PMID 38235131, 2023). "In poorly immunogenic B16 melanoma cells, restoring NLRC5 expression induces MHC-I and elicits antitumor immunity, raising the possibility of using NLRC5 for tumor immunotherapy." (PMID 37108368, 2023). "As NLRC5-SA upregulates MHC-I as strongly as NLRC5-FL, we evaluated the growth of B16 melanoma and EL4 lymphoma cells expressing NLRC5-SA, NLRC5-FL or NLRC5-control vector as tumors in syngeneic C57BL/6 mice." (PMID 37108368, 2023). "We have shown that NLRC5 renders B16F10 mouse melanoma cells highly immunogenic via upregulating MHC-I and APP genes that facilitates the processing and presentation of endogenous tumor antigenic peptides." (PMID 37108368, 2023). "Since the components of the IFN-γ signal transduction and NLRC5 have been linked to MHC class I APM component expression, these molecules were also analyzed in PRELPlow vs. PRELPhigh murine and human melanoma cell lines cells." (PMID 37730606, 2023). "Cells with high basal MHC-I such as MC-38 and B16 melanoma showed a weak response to platinoids alone but that response, including Nlrc5 mRNA and surface MHC-I, was augmented by IFNγ." (PMID 33602823, 2021). "Correlation between NLRC5 expression and infiltrating level of immune cell in melanoma receiving immunotherapy." (PMID 34307322, 2021). "Overexpression of NLRC5 in tumor cells can dramatically enhance their immunogenicity, such as overexpression of Nlrc5 in a mouse model of melanoma resulted in improved tumor clearance." (PMID 34201655, 2021). "At last, melanoma patients with low NLRC5 expression have substantially worse response rates and outcomes to immunotherapy." (PMID 34307322, 2021). "As the loss of MHC-I expression is a common immune escape mechanism in cancers and NLRC5 is the key transcriptional activator of MHC-I genes, our laboratory studied the impact of NLRC5 on antitumor immunity using the B16.F10 murine melanoma model." (PMID 33671123, 2021). "In this study, by analyzing the expression and the transcriptional regulation of NLRC5 in melanoma from GEO (Gene Expression Omnibus), TCGA (The Cancer Genome Atlas), and cBioPortal database, we investigated the clinical significance of NLRC5 in melanoma." (PMID 34307322, 2021). "We explored the biological processes (BPs) and HALLMARKs correlating with NLRC5 expression in melanoma through GSEA (Gene set enrichment analysis)." (PMID 34307322, 2021). "As a result, we used melanoma as another model that mimics a complicated microenvironment and further explored the contributing role of NLRC5 in angiogenesis." (PMID 33754073, 2021). "In summary, these findings suggest that NLRC5 acts as a tumor suppressor in melanoma via modulating the tumor immune microenvironment." (PMID 34307322, 2021). "By evaluating the association between the clinical-pathological characteristics and NLRC5 expression, the clinical-pathological significance of the NLRC5 expression in melanoma was assessed." (PMID 34307322, 2021). "NLRC5 expression was significantly positively associated with both CYT score and the expression of PRF1 and GZMA in all four melanoma datasets." (PMID 34307322, 2021). "And it was also associated with DSS in GSE54467 (log-rank p = 0.019), GSE53118 (log-rank p = 0.008), and GSE65904 (log-rank p = 0.002), indicating the close correlation between low expression of NLRC5 and poor outcomes of melanoma patients." (PMID 34307322, 2021). "NLRC5 expression in multiple tumors, including prostate, lung, uterine, melanoma, and thyroid cancer, was lower than corresponding normal tissues." (PMID 34307322, 2021).
melanoma (continued). "In summary, this study identified the expression of NLRC5 as a novel predictive biomarker for immune checkpoint blockade therapies in melanoma." (PMID 33547395, 2021). "We identify that NLRC5 is expressed in both immune cells and melanoma cells in melanoma samples and its expression is regulated by SPI1 and DNA methylation." (PMID 34307322, 2021). "We then examined the survival of melanoma patients receiving immunotherapy after dividing the patients into two equal groups (high and low NLRC5 expression)." (PMID 34307322, 2021). "We analyzed and compared the gene expression level of NLRC5 and its dependent genes in melanoma between the groups who benefitted from the treatment (responder) and who did not benefit (non-responder)." (PMID 33547395, 2021). "In this study, we revealed that NLRC5 is expressed in both immune cells and melanoma cells in melanoma samples and that its expression was associated with clinical characteristics such as ulceration status, T stages, recurrence, and prognosis." (PMID 34307322, 2021). "Altogether, NLRC5 expression correlates positively with infiltrating level of immune cells in melanoma, especially for CD8+ T cells, which are the preferred immune cells for targeting cancer." (PMID 34307322, 2021). "Altogether, these results suggest the prognostic value of the reduced expression of NLRC5 in melanoma patients." (PMID 34307322, 2021). "In parallel, the overexpression of the NOD-like receptor CARD domain-containing 5 (NLRC5) in melanoma cells enhances antitumor immunity by increasing the expression of MHC class I genes and presentation of tumor antigens." (PMID 32831131, 2020). "NLRC5 has been reported to elicit anti-tumor immunity by enhancing antigen processing and presentation in melanoma." (PMID 32630675, 2020). "Only the module turquoise had a significant enrichment (p = 0.009) of genes whose homologs displayed prognostic value in melanoma, such as Oca2, Samhd1, Nlrc5, Irf1, Ifitm3, Sp100, Dram1, Rtn1, Tcaf2, Parp10, and Grin3a." (PMID 32831131, 2020). "The authors demonstrate that NLRC5 overexpression in B16 melanoma allows to recover MHC class I expression, rising tumor immunogenicity and counteracting immune evasion." (PMID 27437103, 2016). "In this commentary, we summarize and put into perspective a study by Rodriguez and colleagues recently published in Oncoimmunology, addressing the role of NLRC5 in melanoma." (PMID 27437103, 2016). "As proof of principle, the authors immunized mice with irradiated B16 melanoma cells expressing NLRC5." (PMID 27437103, 2016). "Stable expression of NLRC5-SA in B16-F10 (B16) melanoma cells, which express negligible levels of NLRC5 and MHC-I at steady state, markedly upregulated the expression of MHC-I molecules H-2Kb and H-2Db, albeit to a discernibly lower level than full-length NLRC5 (NLRC5-FL)." (PMID 37108368, 2023). "This indicated that missense mutations of NLRC5 do not seem to impair its ability to mediate the expression of downstream genes in melanoma." (PMID 34307322, 2021). "Our study is unable to distinguish NLRC5 downregulation of which cells in the tumor – infiltrating immune cells or melanoma cells themselves – has a greater contribution to the progression of melanoma and the response of immunotherapy, further work is needed to clarify this question." (PMID 34307322, 2021). "Furthermore, the value of NLRC5 expression in prediction of response to immunotherapy in melanoma was also assessed." (PMID 34307322, 2021). "Nevertheless, our work suggests that the overall expression of NLRC5 in melanoma samples may be a potential new prognostic biomarker, especially for patients receiving immunotherapy." (PMID 34307322, 2021). "Overall, these results suggest that, other than mutation load and neo-antigen load, these results suggest that NLRC5 expression may be a more promising predictive biomarker for response to immunotherapy in melanoma." (PMID 34307322, 2021).
melanoma (continued). "Indeed, NLRC5 has been used in a preclinical model of murine melanoma to restore MHC-I expression, increase tumor immunogenicity and elicit protective antitumor immunity." (PMID 33671123, 2021). "Our study is helpful to understand the intricate crosstalk between NLRC5 and immune regulation and may have implications for improving the immunotherapy of melanoma." (PMID 34307322, 2021). "Characteristics of melanoma patients between NLRC5 low and high groups in TCGA SKCM dataset." (PMID 34307322, 2021). "Furthermore, reduced expression of NLRC5 correlated with poor survival in melanoma and bladder cancer patients, while an inverse correlation was observed in glioma." (PMID 34201655, 2021). "In melanoma, the impact of NLRC5 expression on molecular phenotype, clinical characteristics, and tumor features is largely unknown." (PMID 34307322, 2021). "Additionally, by analyzing the sequencing data from CCLE (Cancer Cell Line Encyclopedia), we showed that NLRC5 is expressed in various cancer cell lines, including melanoma cell lines." (PMID 34307322, 2021). "However, it has also been reported that NLRC5 expression decreased in several solid tumors, such as melanoma, ovarian cancer, breast cancer, and prostate cancer." (PMID 34307322, 2021). "Indeed, NLRC5 expression was detected in the nucleus of some ECs in the vessels of both ischemic limbs and melanoma tumors in mice." (PMID 33754073, 2021). "Interestingly, the authors also tested the use of B16 melanoma cells stably expressing NLRC5 in combination with the co-stimulatory molecule CD80." (PMID 27437103, 2016). "B16 cells exhibit high mutation rate, as melanoma in general, and reversible downregulation of the MHC class I-mediated antigen presentation pathway, being therefore well suited to test the immunogenic effects of NLRC5." (PMID 27437103, 2016). "However, the superior activation of Pmel-1 T cells by NLRC5-expressing B16 melanoma strongly supports the idea that the enhanced capacity to present tumor antigens is the genuine cause for the immunogenicity of this cell line." (PMID 27437103, 2016). "Furthermore, upregulation of IFI16, IFI204, and NLRC5 could limit melanoma growth in mice and improve the survival of patients with melanoma." (PMID 37163421, 2023). "However, immunotherapy is effective in melanoma patients with high NLRC5 expression, which means that immunotherapy alone may achieve a good therapeutic effect." (PMID 34307322, 2021). "We hypothesize that the decreased expression of NLRC5 led to reduced expression of MHC genes in melanoma, which would impair the ability of antigen processing and presentation of tumor cells, leading to tumor immune evasion and thus promoting tumorigenesis in melanoma." (PMID 34307322, 2021). "Targeting the NLRC5 related pathway might improve efficacy of immunotherapy for melanoma patients." (PMID 34307322, 2021). "Moreover, we also observed a low activity of apoptosis in low NLRC5 expression melanoma, suggesting that melanoma with low NLRC5 expression might be chemo/radio-resistant." (PMID 34307322, 2021). "Additionally, NLRC5 expression correlates with immunotherapy efficacy in melanoma." (PMID 34307322, 2021). "It is reported that the melanoma response to antitumor immunity is defined by PRMT5 modulation of the cGAS/STING and NLRC5 pathways." (PMID 40777599, 2025). "PRMT5 methylates IFN-γ inducible protein 16 (IFI16) and suppresses NLRC5 transcription, inhibiting the cGAS-STING and MHCI pathways in melanoma, thereby weakening IFN signaling and antitumor immune responses." (PMID 40166469, 2025). "Kalbasi, Ribas and colleagues previously used overexpression of NLRC5 to rescue APM component expression and ICB sensitivity in Jak-knockout B16 mouse models of melanoma." (PMID 38231444, 2024). "B16 melanoma and EL4 lymphoma tumors expressing NLRC5-SA are controlled as efficiently as those expressing full-length NLRC5 (NLRC5-FL)." (PMID 37108368, 2023).